RNF38 (ring finger protein 38)
Description:
Exhibits preference for UBE2D2 as a E2 enzyme.
Tractability: Small molecule: a structure with a bound ligand is known. PROTAC: ubiquitination databases record sites on it.
Gene: Protein-coding gene on chromosome 9 (36,336,396 to 36,487,548, reverse strand). Ensembl gene ENSG00000137075.
Subcellular location: Nucleus
Subcellular location (Human Protein Atlas): Nucleoplasm
Gene Ontology:
Molecular function: protein binding; ubiquitin protein ligase activity
Biological process: protein ubiquitination; male gonad development
Cellular component: nucleoplasm; nucleus; sperm flagellum
Genetic constraint (gnomAD): Loss-of-function variants: 13 observed, 54.18 expected, observed/expected ratio (o/e) 0.24, 90% interval 0.16 to 0.38. The upper end of that interval is the gene's LOEUF score, 0.38, which puts it in group 1 of 6, group 1 being the genes least tolerant of losing a copy. Missense variants: 476 observed, 581.36 expected, observed/expected ratio (o/e) 0.82, 90% interval 0.76 to 0.88. Synonymous variants: 196 observed, 203.42 expected, observed/expected ratio (o/e) 0.96, 90% interval 0.86 to 1.09.
Homologues: Orthologues: macaque RNF38 (99% identical), chimpanzee RNF38 (99% identical), pig RNF38 (99% identical), dog RNF38 (99% identical), guinea pig RNF38 (97% identical), rat Rnf38 (97% identical), mouse Rnf38 (88% identical), tropical clawed frog rnf38 (86% identical), zebrafish rnf38 (72% identical). Paralogues in human: RNF44 (51% identical), RLIM (19% identical), RNF6 (18% identical).
Diseases named in the same sentence as RNF38 in open-access papers:
RNF38 is named in the same sentence as 21 diseases in open-access papers, as found by Europe PMC text mining. Sharing a sentence is not in itself a finding about the gene and the disease. The quoted sentences say what the papers report.
hepatocellular carcinoma (6 papers, 2019 to 2023). A malignant tumor that arises from hepatocytes. "Previous studies suggested that RNF38 promoted the progression of hepatocellular carcinoma, gastric cancer, and non-small-cell lung cancer." (PMID 35568845, 2022). "The rate of RNF38 expression increased in liver carcinoma cells." (PMID 36819206, 2022). "Furthermore, AHNAK knockdown restored the reduced migratory and invasive capacity of HCC cells due to RNF38 downregulation, which appears to indicate the presence of AHNAK as an oncogenic factor in hepatocellular carcinoma." (PMID 38033502, 2023). "RNF38, a member of the RNF protein family, is considered to be important for cancer progression in various tumors including cervical cancer, hepatocellular carcinoma, and NSCLC." (PMID 37626047, 2023). "Using frozen tumor tissue and tissue microarray from hepatocellular carcinoma (HCC) patients, we tried to probe the expression of RNF38 in HCC and its clinical value." (PMID 30836988, 2019).
non-small cell lung carcinoma (3 papers, 2018 to 2022). A group of at least three distinct histological types of lung cancer, including non-small cell squamous cell carcinoma, adenocarcinoma, and large cell carcinoma. "For example, rnf38 mRNA and protein levels are upregulated in non-small cell lung cancer (NSCLC), which in turn increases proliferation and the metastatic capacity of the cells, whereas rnf38 mRNA is increased in the hypothalamus during ageing." (PMID 30574074, 2018).
cervical carcinoma (2 papers, 2022 to 2023). A carcinoma arising from either the exocervical squamous epithelium or the endocervical glandular epithelium. "In addition, RNF38 significantly inhibited the growth of cervical carcinoma cells." (PMID 35568845, 2022).
nasopharyngeal carcinoma (2 papers, 2022 to 2023). A carcinoma arising from the nasopharyngeal epithelium. "Through previous literature, it is known that RING finger protein 38 (RNF38) ubiquitinates ACTN4 in nasopharyngeal carcinoma, leading to the degradation of ACTN4 and inhibiting tumor proliferation and metastasis." (PMID 37626047, 2023). "However, RNF38, a member of the RNF protein family, has not been studied in nasopharyngeal carcinoma (NPC)." (PMID 35568845, 2022).
aplastic anemia (1 paper, 2023). Anemia resulting from bone marrow failure (aplastic or hypoplastic bone marrow). "For instance, the ubiquitin ligase STUB1 regulates the stability and activity of RUNX1 in leukemia; RNF38 promotes RUNX1 ubiquitination and enhances RUNX1-mediated erythroid transcriptional program inhibition; while FZR1 regulates ubiquitin-dependent degradation of RUNX1 in aplastic anemia." (PMID 36949071, 2023).
asthenozoospermia (1 paper, 2022).
colorectal cancer (1 paper, 2022). A primary or metastatic malignant neoplasm that affects the colon or rectum. "Our study indicated that RNF38 exhibited a negative effect on growth and metastasis in NPC by suppressing NF-κB and MAPK activation instead of activating the NF-κB pathway by RNF20 or RNF183 in colorectal cancer." (PMID 35568845, 2022).
depression (1 paper, 2018). "Since the deregulation of UPS is suggested to be involved in social behaviour and neurological disorders such as depression, the identification of RNF38 ubiquitin ligase pathways that control the 5-HT system could advance our understanding in these neurological disorders." (PMID 30574074, 2018).
gestational diabetes mellitus (1 paper, 2021). "It has been reported that CA rebalances insulin sensitivity and inflammatory response in gestational diabetes mellitus by suppressing ring finger protein 38 (RNF38) expression." (PMID 34737695, 2021).
Infertility (1 paper, 2022).
liver cancer (1 paper, 2021). An epithelial or non-epithelial malignant neoplasm that arises from the liver. "In liver cancer, RNF38 was shown to induce cellular EMT by promoting TGF-β signaling through AHNAK ubiquitination and degradation." (PMID 34689136, 2021).
lymphoma (1 paper, 2020). A malignant (clonal) proliferation of B- lymphocytes or T- lymphocytes which involves the lymph nodes, bone marrow and/or extranodal sites. "We examined the 19 cases with associated SVs for fusions involving either CD274 or PDCD1LG2, and we identified a putative fusion transcript for RNF38->PDCD1LG2 involving three cases, all of which were lymphoma." (PMID 32024823, 2020).
melanoma (1 paper, 2019). A malignant, usually aggressive tumor composed of atypical, neoplastic melanocytes. "Recently, a report suggested that the knockdown of AHNAK in a melanoma cell line led to the loss of cadherin-1 and was associated with poor patient outcomes, providing evidence that upregulated RNF38 induced a reduction in E-cadherin levels rather than directly interacting with E-cadherin." (PMID 30836988, 2019).
Ventricular hypertrophy (1 paper, 2022). Enlargement of the cardiac ventricular muscle tissue with increase in the width of the wall of the ventricle and loss of elasticity. "However, we were able to detect prolonged QRS, ST and QTc intervals in heterozygous Rnf38 mutants, potentially indicating ventricular conduction delay and abnormal depolarization, while homozygous loss of Rnf38 resulted in ventricular hypertrophy and early embryo lethality." (PMID 39195995, 2022).
cancer (8 papers, 2018 to 2023). A tumor composed of atypical neoplastic, often pleomorphic cells that invade other tissues. "Importantly, IHC analysis of the serial sections showed that cancer cells from aggressive margins had higher levels of RNF38, vimentin and snail and loss of E-cadherin in both HCC and transplanted tumor tissues, strongly suggesting that cells with elevated RNF38 expression underwent EMT." (PMID 30836988, 2019). "An increase in RNF38 expression is related to cancer invasion and progression, as well as the inhibition of apoptosis in vivo and within the body." (PMID 36819206, 2022). "RNF38 plays a potential cancer suppressor gene role in NPC tumorigenesis and is a prognostic biomarker in NPC." (PMID 35568845, 2022). "For instance, in our previous study, we demonstrated that RING finger protein 38 (RNF38) potentially promotes cancer invasion and metastasis by inducing EMT in HCC." (PMID 32951492, 2020). "The formation of this fusion might change the function of RNF38, which reportedly promotes cancer cell migration and invasion, inhibition of cancer cell apoptosis, and epithelial-mesenchymal transition." (PMID 36812239, 2023). "RNF38 was reported as a vital driver of cancer progression and could promote the invasion and metastasis of cancer cells." (PMID 36812239, 2023). "RNF38 has been suggested to play an important role in cancers." (PMID 35415236, 2022). "We found that RNF38 acts as a potential cancer suppressor gene in NPC." (PMID 35568845, 2022). "As RING finger E3s play a crucial role in cancer metastasis, we wondered whether RNF38 was involved in the process of NPC metastasis." (PMID 35568845, 2022). "However, as a member of the RNF family, the role of RNF38 (ring finger protein 38) in cancers remains unclear and awaits further identification." (PMID 35568845, 2022). "Therefore, the role of RNF38 remains to be validated in more cancers." (PMID 35568845, 2022). "Thus, there is a growing need to determine the detailed molecular mechanism of RNF38 in cancer." (PMID 30836988, 2019). "RING finger protein 38 (RNF38) is widely expressed in human tissues and belongs to the RNF protein family that plays significant roles in the physiology and pathologies of human cancers." (PMID 35415236, 2022). "RING finger protein 38 (RNF38), a member of the RNF protein family, has just emerged as a vital driver of cancer progression." (PMID 30836988, 2019). "The results revealed that both RNF38 and AHNAK were present in the cytoplasm of HCC cells, and that positive TGFBR1 staining was mainly localized in the membrane and cytoplasm of cancer cells." (PMID 30836988, 2019). "However, the role of RNF38 in cancer remains unknown until now." (PMID 30477559, 2018). "Besides, we found that miR-377-3p functioned as a carcinoma inhibitor by inhibiting cell activity and mobility and stimulating apoptosis of HCC cells via regulating RNF38." (PMID 35415236, 2022).
tumor (7 papers, 2018 to 2025). "The human genome contains two genes that are related to mura, RNF38 and RNF44, which have been associated with both pro- and anti-tumour cell activity and drug resistance." (PMID 40867527, 2025). "Then, we sought to explore the downstream signal transduction mechanisms by which RNF38 acts as a tumor suppressor in NPC." (PMID 35568845, 2022). "We found that the average xenograft tumor volume and tumor weight was significantly decreased in RNF38 overexpressing cells (RNF38) compared with control cells (NC), and vice versa." (PMID 35568845, 2022). "Our study suggested that, like RNF43 and RNF20, RNF38 plays a tumor-suppressing role in NPC and is supposed to be a potential biomarker for predicting recurrence and metastasis according to our study." (PMID 35568845, 2022). "To further confirm the functions of RNF38 in the tumor-promoting effects of EBV-miR-BART8-3p, we rescued RNF38 expression in CNE-1-BART8-3p and SUNE-1-BART8-3p cells." (PMID 30477559, 2018). "The expression level of RNF38 in tumor samples was significantly lower than that in normal tissue." (PMID 37681027, 2023). "Our study indicated that RNF38 functions as a tumor suppressor." (PMID 35568845, 2022). "By combining these findings with those of studies indicating the tumor-promoting effects of increased RNF38 expression in clinical and animal models, we conclude that the level of RNF38 modulates cell responsiveness to TGF-β, thus playing an important role in HCC development." (PMID 30836988, 2019). "Importantly, Cox regression analysis indicated that tumor size, embolus, and the RNF38 staining level are independent prognostic factors for HCC patients." (PMID 30836988, 2019). "In addition, the expression of RNF38 decreased with the progression of the tumor stage." (PMID 37681027, 2023). "Our data showed that RNF38 might act as a tumor suppressor in NPC." (PMID 30477559, 2018). "RNF38, a member of the RNF protein family, is abundant in the human testis, and its dysfunction is involved in a variety of human disorders, particularly neoplasms." (PMID 30836988, 2019). "Besides, the silencing of circ-CFH inhibited RNF38 and circ-CFH expression while it enhanced miR-377-3p expression in xenograft tumor tissues." (PMID 35415236, 2022). "Further analyses indicated that high levels of RNF38 expression were significantly correlated with large tumor size (p = 0.008), the absence of tumor encapsulation (p = 0.004), the presence of embolus (p = 0.030), and advanced TNM stage (p = 0.019)." (PMID 30836988, 2019). "Furthermore, the correlation analysis indicated a strong negative correlation between RNF38 and AHNAK protein levels in tumor tissues from HCC patients." (PMID 30836988, 2019).
RNF38 also shares sentences with these, for which no sentence is quoted: Cachexia (1 paper); gastric cancer (1); leukemia (1); lung carcinoma (1); neurological disorders (1).